BIRC6 (baculoviral IAP repeat containing 6)
Diseases named in the same sentence as BIRC6 in open-access papers (continued):
Sharing a sentence is not in itself a finding about the gene and the disease.
infection (4 papers, 2008 to 2025). The state of being infected such as from the introduction of a foreign agent such as serum, vaccine, antigenic substance or organism. "This genetic change is linked with the production of a modified form of BIRC6 in infection-fighting immune cells called monocytes." (PMID 35866869, 2022). "This modulation of invasive bacterial disease risk, despite diverse sources and routes of infection and diverse mechanisms of invasion, suggests a mechanism in which genetic variation at BIRC6 modifies risk of invasive infection downstream of initial mechanisms of infection and invasion." (PMID 35866869, 2022). "It is highly plausible that BIRC6 could determine susceptibility to invasive infection through either its regulation of apoptosis or autophagy (or both)." (PMID 35866869, 2022).
bacterial disease (2 papers, 2022 to 2023). "The analyses found that children with a variation in the BIRC6 gene on chromosome 2 had a higher risk of bacterial infections." (PMID 35866869, 2022). "We further demonstrate that rs183868412 mediates risk of invasive bacterial disease through the modification of BIRC6 splicing in Pam3CSK4-stimulated monocytes." (PMID 35866869, 2022). "Studies have shown that the BIRC6 mutation increases the risk of bacterial infections in children." (PMID 36768802, 2023). "Thus, increased risk of invasive bacterial disease may be associated with decreased expression of an alternative BIRC6 transcript in TLR1/2-stimulated monocytes." (PMID 35866869, 2022). "In doing so, we increase our study power and identify BIRC6 as a novel genetic determinant of invasive bacterial disease in Kenyan children." (PMID 35866869, 2022). "Taken together, our data identify a role for BIRC6 in the pathogenesis of invasive bacterial infections in Kenyan children." (PMID 35866869, 2022).
neurodegenerative disease (1 paper, 2011). A disorder of the central nervous system characterized by gradual and progressive loss of neural tissue and neurologic function. "Association of PDIA5 and BIRC6 (as well as PSMB7 and CYP1B1 in the Salt Lake City population) with POAG indicates that adult-onset glaucoma belongs to the same category of late onset neurodegenerative diseases." (PMID 21655191, 2011).
BIRC6 also shares sentences with these, for which no sentence is quoted: non-small cell lung carcinoma (6 papers); colorectal adenoma (3); lymphoma (3); bladder cancer (2); diabetes (2); dysplasia (2); Hyperkeratosis (2); oral lichen planus (2); thyroid cancer (2); acute leukemia (1); acute lymphoblastic leukemia (1); Alzheimer disease (1); Ductal Carcinoma in situ (1); Epithelial Dysplasia (1); glioblastoma (1); Hepatic steatosis (1); leukemia (1); lichen planus (1); liver disease (1); malaria (1); male infertility (1); mesothelioma (1); Miscarriage (1); neurological disorders (1); oral epithelial dysplasia (1); osteosarcoma (1); Ovarian Insufficiency (1); pediatric acute myeloid leukemia (1); primary angle-closure glaucoma (1); pseudoexfoliative glaucoma (1).
A further 4 diseases each share a sentence with BIRC6 in 1 paper.